VASH1 (vasohibin 1)
Diseases named in the same sentence as VASH1 in open-access papers (continued):
Sharing a sentence is not in itself a finding about the gene and the disease.
malignant neoplasms of the pancreas (1 paper, 2022). "The association between the location of the tumor in the pancreas and the concentration of VASH-1 and VASH-2 was also found in other malignant neoplasms of the pancreas." (PMID 35372578, 2022).
melanoma (1 paper, 2009). A malignant, usually aggressive tumor composed of atypical, neoplastic melanocytes. "Murine VASH1-overexpressing B16F10 melanomas displayed a reduction in large vessels and vascular area." (PMID 19682397, 2009).
ovarian clear cell cancer (1 paper, 2015). An invasive malignant neoplasm that arises from the ovary and is characterized by a predominance of clear and hobnail malignant epithelial cells. "It inhibited the migration, increased the vasohibin-1 expression, and decreased the IGF-1 expression in not only ES-2 cells but also in another ovarian clear cell carcinoma JHOC-5 cells." (PMID 26360832, 2015).
pancreatic cancer (1 paper, 2022). "Other authors have also shown that in pancreatic cancer, VASH-1 expression is regulated by TGF-β/BMP (transforming growth factor-beta/bone morphogenetic protein) signaling." (PMID 35372578, 2022).
pancreatic NENs (1 paper, 2022). "In the NEN group, the highest concentration of VASH-1 was in patients with pancreatic NENs in relation to NENs with different location of the primary tumor (p < 0.05)." (PMID 35372578, 2022).
pancreatic NETs (1 paper, 2022). "Our study showed a significantly higher concentration of VASH-1 in the blood serum of the pancreatic NETs as compared to the other tumor locations." (PMID 35372578, 2022).
pulmonary diseases (1 paper, 2012). "It would be therefore interesting to see if there is any relationship between those pulmonary diseases and VASH1." (PMID 23056314, 2012).
squamous cell carcinoma (1 paper, 2018). A carcinoma arising from squamous epithelial cells. "The plasma VASH1 levels of patients with adenocarcinoma were 282.9 ± 180.2 fmol/mL, and those of patients with squamous cell carcinoma were 302.0 ± 190.7 fmol/mL." (PMID 30623077, 2018).
type 1 diabetes (1 paper, 2014). "In the present study, we utilized a VASH1+/− mouse model of streptozotocin-induced type 1 diabetes." (PMID 25255225, 2014).
type 2 diabetic nephropathy (1 paper, 2017). "Based on both the antiangiogenic and the endothelial protective effects of VASH1, we evaluated the therapeutic effects of VASH1 in type 1 and type 2 diabetic nephropathy mouse models." (PMID 28835895, 2017).
tumor (45 papers, 2009 to 2026). "The LinkedOmics website was used to study the association between VASH1 expression and tumor purity." (PMID 38010374, 2023). "VASH1 inhibits the growth of tumor cells, and overexpression of VASH1 can cause apoptosis (cell death) of dividing cells." (PMID 36504559, 2022). "Forest plots showed that VASH1 had significant effects on the survival time of specific tumor types, with VASH1 associated with OS and DSS in LGG patients (P=0.008 andP=0.014)." (PMID 36504559, 2022). "This is in accordance with earlier reports of Vash1 being highly expressed in angiogenic vessels, healthy or tumour associated, in vitro and in vivo as well as in arteries." (PMID 33547133, 2021). "A recent study demonstrated that EZH2 silencing in tumor-associated endothelial cells inhibited angiogenesis via the reactivation of VASH1." (PMID 26452129, 2015). "We isolated normal ECs from WT mice or tumor associated ECs from WT and VASH1 (−/−) mice, and compared the expression of VASH1." (PMID 24066086, 2013). "So far, the therapeutic effect of VASH1 has been shown in at least the following three different conditions; tumor angiogenesis, arterial adventitial angiogenesis associated with intimal thickening and ocular angiogenesis." (PMID 27713261, 2010). "Clinically, VASH-1 serves both as a diagnostic marker (e.g., serum biomarker and tissue-based prognostic indicator) and a therapeutic target (such as improving renal disease or promoting tumor vascular normalization)." (PMID 41737219, 2026). "Notably, despite its anti-angiogenic role in ECs, elevated VASH1 expression in tumor blood vessels has been associated with poorer oncological prognosis and increased tumor recurrence, suggesting a complex role in tumor progression." (PMID 40483461, 2025). "In addition, the expression of regulators associated with tumor metastasis or angiogenesis, such as Vasohibin-1 (VASH1), is also affected in cells transfected with miR-143-3p." (PMID 38053093, 2023). "In addition, we used the R package estimate to evaluate the matrix score for each tumor sample, and the VASH1 expression levels were significantly associated with LGG (R = 0.165 and P=0.020)." (PMID 36504559, 2022). "Recently, VASH1 was found to mediate tubulin detyrosination, a post-translational modification that allows the discrimination of mitotic errors that need to be corrected to prevent chromosomal instability, and is implicated in tumor evolution and metastasis." (PMID 35145607, 2022). "Finally, circulating exosomal miR-221-3p levels also have biological function in promoting HLECs sprouting in vitro and are closely associated with tumor miR-221-3p expression, lymphatic VASH1 expression, lymphangiogenesis, and LN metastasis in CSCC patients." (PMID 30254211, 2019). "We previously reported that VASH1 was specifically expressed in activated vascular ECs and was associated with tumor malignancy such as GS, pT stage, and was an independent predictor of tumor progression in PCa." (PMID 29535800, 2018). "In addition, recent studies using recombinant adenovirus encoding VASH1 have shown that VASH1 inhibited tumor growth and metastasis in vivo." (PMID 25797264, 2015). "KEGG analysis showed that VASH1 is associated with cell adhesion factors, Hippo signaling, T cell receptor signaling, endothelial cell migration, and cholesterol synthesis, which indicate that VASH1 is associated with extracellular mechanisms and cellular interactions of the tumor microenvironment." (PMID 36504559, 2022). "The interplay between VASH1 and VASH2 underscores their potential as prognostic biomarkers, with VASH1 levels in circulating white blood cells (WBCs) possibly indicating anti-angiogenic capacity, tumor behavior, and response to therapies." (PMID 40483461, 2025). "After tumor resection, plasma VASH1 levels were significantly downregulated (2233 ± 1464 pg·mL−1 vs. 2425 ± 1493 pg·mL−1, p = 0.0085), while plasma VASH2 levels remained unchanged in HNSCC patients." (PMID 40483461, 2025).
tumor (continued). "For example, in breast ductal carcinoma, VASH-1 overexpression reduced tumor microvessel density by 58% and decreased xenograft growth by 42%." (PMID 40497943, 2025). "Plasma VASH1 levels were significantly reduced after tumor resection, 2233 ± 1464 pg·m−1 vs. 2425 ± 1493 pg·m−1 (0.90 ± 0.07 fold, p = 0.0085 by Wilcoxon signed-rank test; Kolmogorov–Smirnov test, p < 0.0100)." (PMID 40483461, 2025). "This is understandable, for if VASH1 is related to tumor vascular quality, in natural disease course, high VASH1 tumors are likely to have a stable vascular structure, enabling growth and circulation of tumor cells." (PMID 38376711, 2024). "VASH1 has multiple functions including increasing chemosensitivity to PTX in tumor cells and abrogating angiogenesis in the tumor microenvironment." (PMID 39710372, 2024). "VASH1 and VASH2 have been reported to function differently, with VASH1 inhibiting angiogenesis and tumor metastasis, whereas VASH2 promotes angiogenesis and tumor progression." (PMID 39443476, 2024). "Multivariate analysis showed that MVD and VASH1 remained independent predictive factors for tumor elimination." (PMID 38376711, 2024). "Functional enrichment analysis suggests that VASH1 plays a tumor suppressor role by regulating the extracellular matrix receptor pathway." (PMID 38010374, 2023). "Given that immunotherapy is a key treatment for tumor reduction and eradication, the relationship between VASH1 expression and the expression of the 47 immune checkpoint genes was further analyzed." (PMID 36504559, 2022). "In in vitro experiments, since it is impossible to mimic the tumor microenvironment, where alteration of certain factors can directly affect tumor proliferation and growth, VASH1 acts as its endogenous antitumor effect in vitro." (PMID 36504559, 2022). "With the continuous progress of research on VASH1, more and more scholars have developed the special biological characteristics of VASH1 and applied them to clinical treatment as a tumor target." (PMID 36504559, 2022). "Next, we investigated the relationship between VASH1 and tumor purity according to the ESTIMATE algorithm." (PMID 36504559, 2022). "Tumor growth, histological characteristics, blood vessel volume, and VASH1 and 2 expressions were analyzed." (PMID 35145607, 2022). "In this study, we confirmed the correlation between VASH1 and LGG tissue expression, WHO grade, IDH1 mutation, tumor mutation burden (TMB), immune cell infiltration, and prognosis by using TCGA, GTEx, CCLE, CGGA, UALCAN, GEPIA2, and Timer databases." (PMID 36504559, 2022). "Recent studies have shown that VASH1 can be selectively expressed not only in endothelial cells but also in tumor cells and some immune cells, participating in the occurrence and development of tumors and immune responses." (PMID 36504559, 2022). "The univariate analysis showed that tumor recurrence, WHO grade, IDH1 wild-type, and high VASH1 expression were individual risk factors affecting the prognosis of LGG patients." (PMID 36504559, 2022). "This further suggests a potential association of VASH1 with TMB and suggests that VASH1 and TMB function together and are associated with tumor progression." (PMID 36504559, 2022). "We found that VASH1 expression is closely related to the grade of LGG malignancy and tumor recurrence, so does the VASH1 expression level affect the prognosis of LGG patients?" (PMID 36504559, 2022). "VASH1 inhibits the invasion and migration of tumor cells by affecting microtubule formation and immune infiltration in the tumor microenvironment." (PMID 36504559, 2022). "Q3G impaired tumor growth and vascularization, upregulated VASH1, and downregulated VASH2 in comparison to untreated animals." (PMID 35145607, 2022). "The invasion and migration ability of tumor cells are key properties affecting tumor invasion and recurrence, and our previous study confirmed the correlation between VASH1 expression levels and tumor progression." (PMID 36504559, 2022).
tumor (continued). "The status of VASH-1, which represents the neoangiogenesis status, was also reported to suppress TILs and anti-tumor immune responses." (PMID 35565281, 2022). "Although these studies demonstrated that VASH1 is necessary for controlling angiogenesis in a tumour and injury onset in vivo, they predated the discovery of VASH1 as a microtubule-modifying enzyme." (PMID 33547133, 2021). "Conversely, Vash1 knockout mice exhibited more vascularised tumours and increased angiogenesis in the ear skin injury model." (PMID 33547133, 2021). "During tumor development in mice xenograft models, experiments involving the administration of ectopic VASH1 indicated that it inhibits tumor lymphangiogenesis, angiogenesis and growth." (PMID 33114575, 2020). "Treatment with antagomir-494 inhibits angiogenesis and reduces tumour growth in vivo Likewise, miR-4530 increases angiogenesis by targeting vasohibin 1 (VASH1), while miR-127 was protective for I/R related tissue damage." (PMID 30699970, 2019). "Immunofluorescence and ISH in human CSCC tissues also demonstrated that high miR-221-3p levels in tumor were accompanied by reduced VASH1 expression in LYVE1-positive lymphatic vessels and enhanced PLVD." (PMID 30254211, 2019). "Even if the tumor volume was low in biopsy samples, VASH1 density reflected the grade of malignancy throughout the prostate." (PMID 29535800, 2018). "While it can be assumed to derive from tumor vasculature, it is also possible that VASH1 proteins in systemic circulation are derived from the normal vascular bed." (PMID 30623077, 2018). "By multivariate analysis, high VASH1 density was an independent predictor of tumor recurrence and CSS." (PMID 29135410, 2018). "An anticancer effect of VASH1 through its inhibition of tumor angiogenesis has been confirmed in several reports." (PMID 28835895, 2017). "We further utilized the gain-of-function and loss-of-function strategies and discovered that cancer cell-derived VASH1 can directly control tumor cell fate and biological functions through the following actions." (PMID 25797264, 2015). "We observed that knockdown of VASH1 in HCT116 tumor cells markedly increased the adherent ability of tumor cells in the fibronection-coated plates." (PMID 25797264, 2015). "As expected, knockdown of VASH1 in HCT116 cells dramatically increased tumor macrometastatic numbers both in lung and in liver surfaces." (PMID 25797264, 2015). "We observed that patients with lower stroma VASH1 expression levels had bigger tumor sizes, advanced clinical stages, as well as increased other organ metastases." (PMID 25797264, 2015). "Then, we examined other tumor-associated genes, such as c-myc, E-cadherin, TIMP-2, TIMP-3, and VASH1." (PMID 26452129, 2015). "Our studies collectively demonstrate that VASH1 is a tumor suppressor and plays a critical role in directing tumorigenesis and metastasis." (PMID 25797264, 2015). "Knockdown of VASH1 in HCT116 cells dramatically promoted tumor growth, compared with the control shRNA–transfected HCT116 cells." (PMID 25797264, 2015). "VASH1 protein expression levels in different tumor cell lines were further confirmed using western blot analysis." (PMID 25797264, 2015). "We then dissected the potential mechanisms responsible for the inhibition of tumor growth and proliferation induced by VASH1 expression." (PMID 25797264, 2015). "The transmigration result was further confirmed in VASH1 shRNA-transfected HCT116 tumor cells using the wound closure assays." (PMID 25797264, 2015). "As expected, silence of VASH1 expression in HCT116 tumor cells dramatically promoted tumor growth and increased cell proliferation." (PMID 25797264, 2015). "We therefore examined the cellular composition of tumor blood vessels, and reaffirmed our previous observation that tumor blood vessels in VASH1 (−/−) mice are more immature, having fewer mural cells." (PMID 24066086, 2013).
tumor (continued). "We previously demonstrated that exogenous VASH1 inhibited tumor lymphangiogenesis and LN metastasis." (PMID 24066086, 2013). "The expression of VASH1 in ECs of tumor vessels was significantly higher than that in those of normal quiescent vessels in WT mice, while the expression of VASH1 was absent in VASH1 (−/−) mice." (PMID 24066086, 2013). "We then evaluated the regional inguinal LN metastasis 8 days after resection of the tumor-bearing legs, and found that LN metastasis was enhanced in VASH1 (−/−) mice." (PMID 24066086, 2013). "The increased size of primary tumor can be one reason for the augmented metastasis in VASH1 (−/−) mice." (PMID 24066086, 2013). "Histological analyses revealed that vessels of the footpad tumor in VASH1 (−/−) mice were more immature, having fewer mural cells." (PMID 24066086, 2013). "Vasohibin-1 has been shown to suppress angiogenesis in chick chorioallantoic membrane after subcutaneous implantation of matrigel, and in a tumor xenograft model." (PMID 20680097, 2010). "Nonetheless, we showed that VASH1 is prevalent in tumor vessels of non-small cell lung cancers when they are associated with mural cells." (PMID 27713261, 2010). "Apart from its effects on physiological angiogenesis murine VASH1 was also studied in a mouse tumor model to analyze its effects on tumor growth and vascularization." (PMID 19682397, 2009). "In contrast to plasma, which measures systemic levels of VASH1, VASH2, and NO, circulating WBCs actively contribute to tumor-associated immune and angiogenic activities, expressing these markers in direct response to tumor signals." (PMID 40483461, 2025). "In contrast to VASH1, which is closely linked to tumor progression and angiogenesis, VASH2 may play a more restricted or context-dependent role within the HNSCC tumor microenvironment." (PMID 40483461, 2025). "Indeed, VASH-1 prevents tumor growth and metastasis by inhibiting tumor angiogenesis in animal tumor models." (PMID 40497943, 2025). "Vasohibin-1 (VASH-1) is a protein known for its anti-angiogenic properties and is closely associated with various physiological processes, such as vascular development, tumor growth, tissue repair, and fibrosis." (PMID 38791272, 2024). "However, further studies are necessary to clarify the most efficient method to express VASH1 in the tumor or tumor microenvironment in vivo when considering the application of VASH1 overexpression in clinical settings." (PMID 39710372, 2024). "We also studied the effects of VASH1 on tumor purity and immune cell infiltration." (PMID 38010374, 2023). "VASH1 modulates complex patterns of tumor immune responses by regulating immune checkpoint genes." (PMID 36504559, 2022). "However, the VASH1 expression level was correlated with tumor recurrence, WHO grade, and IDH1 wild-type expression level (P < 0.05)." (PMID 36504559, 2022). "At the same time, VASH1 overexpression can increase tumor sensitivity to chemotherapy." (PMID 36504559, 2022). "Therefore, increased Foxp3/CD8, PD-1/CD4, and PD-1/CD8 ratios and VASH-1 expression in the tumor tissues were considered to suppress anti-tumor immunity more markedly in NEC than in non-NEC components of MiNENs." (PMID 35565281, 2022). "At the same time, we found that VASH1 has a clear correlation with TMB in LGG, so we believe that VASH1 can be used as a potential immunotherapy target and reflect the ability and extent of tumor production of neoantigens, predicting the immunotherapy efficacy of LGG." (PMID 36504559, 2022). "Therefore, it is explained that VASH1 regulates the activity of tumor cells and endothelial cells through multiple signaling pathways in different tissues." (PMID 36504559, 2022). "Only few reports so far concern the assessment of VASH-1 in tumor tissue itself." (PMID 35372578, 2022).